CACNA1I (calcium voltage-gated channel subunit alpha1 I)
Diseases named in the same sentence as CACNA1I in open-access papers:
CACNA1I is named in the same sentence as 51 diseases in open-access papers, as found by Europe PMC text mining. Sharing a sentence is not in itself a finding about the gene and the disease. The quoted sentences say what the papers report.
schizophrenia (30 papers, 2015 to 2026). A major psychotic disorder characterized by abnormalities in the perception or expression of reality. "Earlier, the CaV3.3-encoding gene CACNA1I was described as a risk gene for schizophrenia and migraine [4–7, reviewed in 8]." (PMID 40825030, 2025). "In CACNA1I, other partial loss-of-function variants, outside the activation-gate, were reported as risk variants for schizophrenia." (PMID 40825030, 2025). "The CACNA1I gene, encoding the voltage-gated calcium channel Cav3.3, is considered a risk factor for schizophrenia." (PMID 39596417, 2024). "Genome-wide association studies have revealed strong link between the gene encoding CaV3.3, CACNA1I, and schizophrenia." (PMID 35079122, 2022). "As the Merikanto study reported an association of slow spindle activity with genetic variability in CACNA1I, a schizophrenia risk gene known to be implicated in spindle generation, we exploratively additionally aimed to replicate this finding." (PMID 35723738, 2022). "Genome-wide association studies (GWAS), as well as the identification of de novo variants in the CACNA1I gene, have contributed to implicate CACNA1I as a genetic risk factor in schizophrenia (SCZ)." (PMID 32638069, 2020). "CACNA1I, a schizophrenia risk gene, encodes a subtype of voltage-gated T-type calcium channel CaV3.3." (PMID 32066662, 2020). "Gene related to Ca2+ signaling, such as CACNA1I that encode VGCC subunits is associated with schizophrenia and other psychiatric disorders." (PMID 28725167, 2018). "A recent trans-ancestry meta-analyses of Chinese and PGC2 samples (a total of 43,175 cases and 65,166 controls) further supports the association between CACNB2, CACNA1C, CACNA1I genes and schizophrenia." (PMID 29308060, 2018). "CACNA1I was validated as a candidate schizophrenia risk gene, in a genome wide association study by the Schizophrenia Working Group of the Psychiatric Genomics Consortium as one of 108 independent genomic loci that exceed genome-wide significance." (PMID 27756899, 2016). "CACNA1I is linked to 18 Schizophrenia-associated variants according to the NHGRI-EBI Catalog." (PMID 38501113, 2024). "As such, CACNA1I variants proposed to contribute to sleep rhythms are also implicated in the development of complex neuropsychiatric disorders including autism and schizophrenia." (PMID 35928792, 2022). "Alterations in the CACNA1I, have been associated with autism, schizophrenia epilepsy." (PMID 33049985, 2020). "In this report, we aim to determine whether a patient-derived coding mutation (R1346H) in the schizophrenia-associated gene CACNA1I alters sleep spindle oscillations during NREM in vivo, to investigate potential translational markers across species." (PMID 32066662, 2020). "Interesting data from GWAS are related to the Calcium Voltage-Gated Channel Subunit Alpha1 I (CACNA1I) gene whose SNP rs5757717 seems to be commonly associated with schizophrenia and OCD, suggesting that genetic factors could cause some of the comorbidity for these two disorders." (PMID 37627285, 2023). "Thus, CACNA1I loss-of-function variants disrupt neuronal excitability and network activity and may contribute to the development of schizophrenia, autism and/or other complex neuropsychiatric disorders." (PMID 33704440, 2021). "The third member of the T-type channel family, Cav3.3 encoded by CACNA1I, was identified as genetic risk factor in schizophrenia." (PMID 33704440, 2021). "Some have been reported as participants in schizophrenia and neurodegenerative diseases, such as CACNA1I and PNPLA8." (PMID 34440578, 2021). "Another notable common risk variant identified in schizophrenia and related to thalamic function is CACNA1I (or CaV3.3), which encodes a T-type calcium (Ca2+) channel." (PMID 34955759, 2021). "The novel interactors CACNA1I and CACNA1G targeted by nervous system drugs are calcium channels that are known to be associated with Alzheimer’s disease and schizophrenia, respectively." (PMID 32973177, 2020).
schizophrenia (continued). "This expression analysis provided further evidence that supports the involvement of CACNA1I in schizophrenia." (PMID 29308060, 2018). "Our study suggests that CACNA1I is a risk gene for SCZ in Chinese population and provides further evidence that supports the potential role of neuronal calcium signaling in schizophrenia." (PMID 29308060, 2018). "To further explore the potential role of CACNA1I in schizophrenia pathogenesis, we examined CACNA1I expression in hippocampus of SCZ cases and controls." (PMID 29308060, 2018). "Recently, a primary GWAS conducted by the Psychiatric Genomics Consortium-Schizophrenia Workgroup (PGC-SCZ) has made encouraging progress in identifying genetic susceptibility loci, and the CACNA1I gene is reported as a new locus for SCZ in Caucasian." (PMID 28725167, 2018). "Recently, two rare, de novo missense variations, Chr22: 39659492C > T and Chr22: 39665939G > A, were identified in CACNA1I by exome sequencing of trio samples that include 105 schizophrenia probands." (PMID 27756899, 2016). "It has been shown that genes related to Ca2+ signaling, such as the CACNA1C, CACNB2, and CACNA1I genes that encode VGCC subunits, are associated with schizophrenia and other psychiatric disorders." (PMID 26136667, 2015). "CACNA1I, encoding a subunit of calcium voltage-gated channel, has been implicated with schizophrenia although it has not yet been linked to bipolar disorder." (PMID 31694669, 2019). "Expression analysis showed that CACNA1I was significantly up-regulated in hippocampus of SCZ cases compared with controls, implying that dysregulation of CACNA1I may have a role in schizophrenia pathogenesis." (PMID 29308060, 2018). "However, the present study remains a major bottleneck in the validation of larger samples, and a larger sample size could be better demonstrate the role of the CACNA1I gene in the etiology of schizophrenia." (PMID 28725167, 2018). "We found that CACNA1I was significantly up-regulated in hippocampus of SCZ cases compared with controls (P = 0.019), suggesting dysregulation of CACNA1I in schizophrenia cases." (PMID 29308060, 2018). "Our analyses suggest that a single copy of Chr22: 39665939G > A CACNA1I has the capacity to disrupt CaV3.3 channel-dependent functions, including rebound bursting in TRN neurons, with potential implications for schizophrenia pathophysiology." (PMID 27756899, 2016).
epilepsy (14 papers, 2017 to 2026). A brain disorder characterized by episodes of abnormally increased neuronal discharge resulting in transient episodes of sensory or motor neurological dysfunction, or psychic dysfunction. "Thus, our study implicates CACNA1I gain-of-function mutations in neurodevelopmental disorders, with a phenotypic spectrum ranging from borderline intellectual functioning to a severe neurodevelopmental disorder with epilepsy." (PMID 33704440, 2021). "Previously we identified CACNA1I, the gene coding for the T-type voltage-gated calcium channel CaV3.3, as a disease gene for neurodevelopmental disease and epilepsy." (PMID 40825030, 2025). "Our review has further revealed variants in CACNA1C, CACNA1F, CACNA1I, CACNA2D1 and CACNA2D2 as additional genes related to epilepsy." (PMID 33985586, 2021). "Together, our data add CACNA1I to the list of disease genes associated with motor and cognitive impairment with or without epilepsy." (PMID 33704440, 2021). "In our previous study on gain-of-function CACNA1I variants linked to neurodevelopmental disorders with and without epilepsy, we suggested two parallel disease mechanisms that could explain the patients’ phenotypes." (PMID 40825030, 2025). "Three types of T-type calcium channels consisting of Cav3.1, Cav3.2, and Cav3.3 are encoded by CACNA1G, CACNA1H, and CACNA1I genes, respectively, which are expressed in the brain and play essential roles in both physiological and pathological systems, including sleep, pain, and epilepsy." (PMID 34201181, 2021). "Our review has highlighted CACNA1C, CACNA1F, CACNA1I, CACNA2D1 and CACNA2D2 as additional genes for epilepsy, and CACNA2D1 for autism spectrum disorder." (PMID 33985586, 2021). "Previously, we established CACNA1I, the gene coding for CaV3.3, as a disease gene for neurodevelopmental disease with or without epilepsy." (PMID 40825030, 2025).
migraine (4 papers, 2020 to 2025). "This is based on previous studies implicating CACNA1I mutations in neuronal excitability and resultant neurological disorders, coupled with high corticothalamic expression of CACNA1I, and potential connections to established migraine symptom-related neural pathways." (PMID 35928792, 2022). "DGR161 and DGR96 (p.Q1158H, CACNA1I) were found to carry variants in ATP1A4 (p.V146I and p.D685H), respectively, albeit the evidence for a role of this latter gene in migraine is still very limited." (PMID 35928792, 2022). "Interestingly, CACNA1I knockout mice lacking TRN rebound bursting also evidence disrupted sleep spindles, while sleep disorders and sleep deprivation constitute known migraine triggers." (PMID 35928792, 2022).
autism (3 papers, 2020 to 2022). Persistent deficits in social interaction and communication and interaction as well as a markedly restricted repertoire of activity and interest as well as repetitive patterns of behavior. "We show here that the CACNA1I risk variant induces spindle deficits, which corroborated with two recent studies of PTCHD1 and GRIA1, two genes implicated by neuropsychiatric genetics, that abnormal sleep spindle oscillation may underlie neurodevelopmental disorders such as autism and schizophrenia." (PMID 32066662, 2020).
autism spectrum disorder (3 papers, 2018 to 2021). A spectrum of developmental disorders that includes autism, and Asperger syndrome. "rs5750860, located in CACNA1I, has been reported to be associated with autism spectrum disorders by using existing genome-wide association study (GWAS) data and imputation methods." (PMID 28725167, 2018).
Intellectual disability (2 papers, 2024 to 2025). "It is therefore well conceivable that distortion of these sleep spindles, due to either increased or reduced CaV3.3 activity, contributes to the neurodevelopmental delay and intellectual disability in the CACNA1I patients." (PMID 40825030, 2025).
brain tumors (1 paper, 2022). "CACNA1I, a gene involving controlling voltage-gated calcium channels, was significantly down-regulated in brain tumors compared to surrounding normal tissues, and patients with low CACNA1I expression were associated with poor prognosis based on the TCGA database." (PMID 35879727, 2022).
breast carcinoma (1 paper, 2015). "This bioinformatics analysis revealed that different subtypes of VGCCs (CACNA1C, CACNA1D, CACNA1B, CACNA1G, and CACNA1I) are implicated in the development and progression of diverse types of cancer and show dramatic up-regulation in breast cancer." (PMID 26147197, 2015). "For instance, breast cancer showed dramatic upregulation of CACNA1C, CACNA1D, CACNA1B, CACNA1G, and CACNA1I." (PMID 26147197, 2015).
invasive breast carcinoma (1 paper, 2015). A carcinoma that infiltrates the breast parenchyma. "CACNA1I was found in the top 4% to 7% of upregulated genes in invasive breast carcinoma stroma and ductal breast carcinoma in situ epithelia, with p-values of 3.04E-16 and 0.002 and fold changes ranging from 1.586 to 2.35, respectively." (PMID 26147197, 2015). "CACNA1I showed altered expression in invasive breast cancer, myxoid/round cell liposarcoma, and esophageal adenocarcinoma." (PMID 26147197, 2015).
juvenile idiopathic arthritis (1 paper, 2023). Juvenile idiopathic arthritis (JIA) is the term used to describe a group of inflammatory articular disorders of unknown cause that begin before the age of 16 and last over 6 weeks. "A gene-set analysis indicated that IgG glycosylation (TAB1, MGAT3, and CACNA1I) and Response to methotrexate in juvenile idiopathic arthritis (CACNA1I and APOBEC3C) may engage common underlying genetic vulnerabilities." (PMID 37029179, 2023).
psychiatric disorder (7 papers, 2015 to 2022). A disorder characterized by behavioral and/or psychological abnormalities, often accompanied by physical symptoms. "Mutations in genes encoding Cav3 channels (CACNA1G, CACNA1H, and CACNA1I) have been linked to a variety of neurodevelopmental, neurological, and psychiatric diseases designated here as neuronal Cav3 channelopathies." (PMID 32638069, 2020). "Together with genetic associations of CACNA1I (encoding CaV3.3) and to a lesser extent CACNA1H (encoding CaV3.2) with SZ, this suggests that T-Ca2+ channel dysfunction in TRN could represent an early pathological feature of this psychiatric disorder." (PMID 35079122, 2022).
neurodevelopmental disorder (6 papers, 2020 to 2025). A behavioral and cognitive disorder with onset during the developmental period that involves impaired or aberrant development of intellectual, motor, or social functions. "Together, our functional analysis of the CACNA1I variants linked to neurodevelopmental disorders provide evidence for two parallel pathomechanisms contributing to the aetiology of the epileptic phenotype." (PMID 33704440, 2021). "In this study we report heterozygous gain-of-function mutations in CACNA1I associated with a congenital neurodevelopmental disorder of variable severity in three unrelated patients and one family." (PMID 33704440, 2021). "In addition, our data suggest that substantial gain-of-function of CaV3.3 leads to the development of seizures, whereas both gain- and loss-of-function variants of CACNA1I can cause neurodevelopmental disorder." (PMID 40825030, 2025). "CACNA1I GOF channel-gating mutations can cause neurodevelopmental disorders." (PMID 35928792, 2022). "Here, we report three heterozygous CACNA1I missense variants p.(Met1425Val), p.(Ala398Val) and p.(Ala398Glu) as novel disease-causing variants for a neurodevelopmental disorder with or without seizures." (PMID 40825030, 2025). "Here we report three newly identified activation-gate-modifying disease variants of CACNA1I, found in four unrelated patients with neurodevelopmental disorders, with or without seizures." (PMID 40825030, 2025).
tumor (4 papers, 2021 to 2025). "VCGG channels, including CACNA1C, CACNA1D, CACNA1F, CACNA1E, CACNA1A, CACNA1G, CACNA1I, showed significantly higher expression in KIRC than normal cases, whereas CACNA1S and CACNA1H showed higher expression in normal than tumor cases." (PMID 36588677, 2022). "The calcium signaling pathway (hsa04020) contained 23 genes (p = 8.81 × 10−7), including key receptors such as SLC8A2, HTR2C, GRIN1, CACNA1I, and GRIN2B, which regulate intracellular calcium levels and tumor microenvironment dynamics via glutamate interactions." (PMID 40406701, 2025).
neurodegenerative disease (2 papers, 2020 to 2021). A disorder of the central nervous system characterized by gradual and progressive loss of neural tissue and neurologic function. "Further research in required to investigate the role of CACNA1I not only in neurodegenerative diseases but also in HD.Ca2+ dysregulation is known to be one of the pathophysiological mechanisms involved in HD." (PMID 33049985, 2020). "However, there are to no studies investigating the effect of CACNA1I on various neurodegenerative diseases, including HD." (PMID 33049985, 2020).
infection (1 paper, 2007). The state of being infected such as from the introduction of a foreign agent such as serum, vaccine, antigenic substance or organism. "At individual gene expression level several transporter genes (Cacna1i, Slc4a1, Slc15a1) and immune response genes (Igsf4d, Ilf1, Csf2) showed no overlap possibly due to infection kinetics." (PMID 17850650, 2007).
CACNA1I also shares sentences with these, for which no sentence is quoted: developmental delay (3 papers); neurological disorders (3); absence seizures (2); Anxiety (2); bipolar disorder (2); depression (2); epileptic seizures (2); microcephaly (2); adenocarcinoma (1); Alzheimer disease (1); Arthritis (1); Ataxia (1); attention deficit-hyperactivity disorder (1); cancer (1); Cerebellar atrophy (1); Cognitive impairment (1); diabetes (1); encephalopathies (1); endometrial cancer (1); gastric cancer (1); glioma (1); Hemiplegic Migraine (1); Hypertension (1); itch (1); language delay (1); melanoma (1); mental disorder (1); Motor delay (1); Neurodevelopmental delay (1); neuromuscular disease (1).
A further 6 diseases each share a sentence with CACNA1I in 1 paper.